PRLR (prolactin receptor)
Diseases named in the same sentence as PRLR in open-access papers (continued):
Sharing a sentence is not in itself a finding about the gene and the disease.
infection (8 papers, 2008 to 2025). The state of being infected such as from the introduction of a foreign agent such as serum, vaccine, antigenic substance or organism. "The PRLR expression in the infection group was significantly higher than that in the control group at 24 h and 48 h (P < 0.05)." (PMID 34998433, 2022). "Using an acute experimental model, we observed changes inGR/PRLR cross-activation related with the survival of CD4+CD8+thymocytes during infection." (PMID 24324845, 2013). "The expression of dPRLR in the spleen and bone marrow in positive LF individuals was higher than that in negative LF individuals, and the expression of PRLR in DF-1 cells was significantly increased after infection with ALV-J." (PMID 34998433, 2022). "After infection with ALV-J, the expression of PRLR in DF-1 cells significantly increased." (PMID 34998433, 2022). "After infection with ALV-J, PRLR and SPEF2 expression in DF-1 cells was evaluated." (PMID 34998433, 2022). "PRL pretreatment of cells starting 3 h before or at the time of infection did not alter PRLR transcript levels." (PMID 32121009, 2020). "PRLR transcript levels were significantly increased in infected cells at 3 and 5 dpi, but not at 1 dpi (with sufficient infection efficiency as in Section 2.1)." (PMID 32121009, 2020).
metabolic disorders (3 papers, 2015 to 2024). "Our hypothesis was that the absence of PRLR induces changes in gut microbiota diversity and composition, promoting a microbial profile potentially linked to an increased risk of developing metabolic diseases." (PMID 37571383, 2023).
benign tumors (2 papers, 2015 to 2016). "Non-neoplastic tissue of fresh frozen samples exhibited significantly higher expression of PRLR than benign tumors (p = 0.005)." (PMID 27649560, 2016). "Only PRLR gene expression was significantly decreased concurrently with the formation of benign tumors." (PMID 26370564, 2015).
adenocarcinoma (1 paper, 2012). A common cancer characterized by the presence of malignant glandular cells. "Adenocarcinomas as well had significantly reduced PRLR expression levels compared to non-neoplastic tissues (p = 0.008)." (PMID 22647582, 2012).
PRLR also shares sentences with these, for which no sentence is quoted: hyperprolactinaemia (4 papers); gynecological cancers (3); carcinoma in situ (2); colon carcinoma (2); Galactorrhea (2); hepatocellular carcinoma (2); hypothyroidism (2); kidney (2); Microprolactinoma (2); parathyroid adenoma (2); rheumatoid arthritis (2); acromegaly (1); acute myeloid leukemia (1); anaplastic carcinoma (1); asthenozoospermia (1); autosomal dominant retinitis pigmentosa (1); Azoospermia (1); bladder cancer (1); bone metastasis (1); Breast Diseases (1); CNS tumors (1); Cryptozoospermia (1); cyst (1); endocervical adenocarcinoma (1); exfoliation glaucoma (1); female infertility (1); gastrinoma (1); Headache (1); headache disorder (1); Hodgkins lymphoma (1).
A further 30 diseases each share a sentence with PRLR in 1 paper.